MIR548N (microRNA 548n)
Synonyms: hsa-mir-548n; MIRN548N
Gene: MicroRNA gene on chromosome 7 (34,940,760 to 34,940,834, reverse strand). Ensembl gene ENSG00000221669.
Homologues: Orthologues: chimpanzee ptr-mir-548n (97% identical), chimpanzee MIR548N (96% identical). Paralogues in human: MIR548H3 (89% identical), MIR548AN (87% identical), MIR548AZ (87% identical), MIR548AY (84% identical), MIR548K (84% identical), MIR548Z (84% identical), MIR548X2 (83% identical), MIR548AA1 (81% identical), MIR548P (81% identical), MIR548F3 (80% identical), MIR548F1 (79% identical), MIR548AH (76% identical), and 13 more.
Diseases named in the same sentence as MIR548N in open-access papers:
MIR548N is named in the same sentence as 1 disease in open-access papers, as found by Europe PMC text mining. Sharing a sentence is not in itself a finding about the gene and the disease.
MIR548N shares sentences with these, for which no sentence is quoted: schizophrenia (1 paper).